TMBIM7P (transmembrane BAX inhibitor motif containing 7, pseudogene )
Gene: Long non-coding RNA gene on chromosome 7 (92,412,550 to 92,447,813, reverse strand). Ensembl gene ENSG00000293397.
Diseases named in the same sentence as TMBIM7P in open-access papers:
TMBIM7P is named in the same sentence as 1 disease in open-access papers, as found by Europe PMC text mining. Sharing a sentence is not in itself a finding about the gene and the disease.
TMBIM7P shares sentences with these, for which no sentence is quoted: virus infection (1 paper).